MET (MET proto-oncogene, receptor tyrosine kinase)
Diseases named in the same sentence as MET in open-access papers (continued):
Sharing a sentence is not in itself a finding about the gene and the disease.
lung cancer (continued). "Furthermore, one study detailed a mechanism for such MET-mediated resistance by showing that an EGFR TKI-sensitive lung cancer cell line can develop resistance to gefitinib as a result of MET amplification via human epidermal growth factor receptor 3 (HER3)-dependent activation of PI3K." (PMID 25962919, 2015). "In the present study, we found that miR-206 was dramatically down-regulated in lung cancer tissues compared with matched normal lung tissues, and it inhibited the tumorigenic potential of lung cancer cells by down-regulating oncogenic targets, such as MET and Bcl2." (PMID 26325180, 2015). "Additionally, significant associations were observed between MET overexpression and locoregional failure, distant metastasis and death in patients with locoregionally advanced NPC, consistent with previous observations in gastric and lung cancer." (PMID 25965822, 2015). "However, data in renal cell and lung carcinomas suggest that somatic and germline MET polymorphisms may enhance c-Met TKR activity and even confer inhibitor resistance." (PMID 25593979, 2014). "Cell line experiments have also shown that both EGFR and MET activation and the interaction between the corresponding signaling pathways may mediate crizotinib resistance, suggesting that both signaling by EGFR and MET may be crucial for the survival of lung cancer cells upon ALK inhibition." (PMID 24279718, 2013). "Moreover, immunoprecipitation analysis revealed that each of these RTKs formed a heterodimer with MET, demonstrating for the first time that EGFR, HER2, HER3, and RET are the main heterodimerisation partners of MET in MET amplification-positive lung cancer cells." (PMID 21847121, 2011). "Importantly, erlotinib may still have clinical utility in this context of combined inhibition with MET inhibitor in EGFR-TKI-resistant lung cancer." (PMID 19238632, 2008). "Our results also implicate that combination treatment using a MET inhibitor plus a reversible or irreversible EGFR kinase inhibitor to achieve dual MET–EGFR inhibition may represent an alternative strategy to circumvent T790M-EGFR-mediated resistance in lung cancer." (PMID 19238632, 2008). "Specifically, in the field of lung cancer, this catalog advocates the inclusion of PD-L1, EGFR, ALK, ROS-1, KRAS, NTKR, RET, and MET." (PMID 40261489, 2025). "For the first time, the current study reported that rapamycin has a binding affinity with ALK, EGFR, FGFR, MET, and ROS1 receptors expressed in the lung cancer cells." (PMID 39762538, 2025). "In lung cancer, anaplastic lymphoma kinase (ALK) was detected in 14% (17/118), and c-MET was detected in 61% (78/128)." (PMID 40075672, 2025). "In our cohort, among the patients with lung cancer, ALK was detected in 14% (17/118), and c-MET was detected in 61% (78/128)." (PMID 40075672, 2025). "This aligns with previous findings that the MET inhibitor PHA-665752 reduces pEGFR levels, while gefitinib has minimal impact in MET-amplified lung cancer cells." (PMID 41315241, 2025). "Discovery and drug development of new lung cancer‐related targets: EGFR, ALK, ROS1, RET, MET, BRAF inhibitors, etc." (PMID 40135802, 2025). "MET is a potential therapeutic target in NSCLC and can promote lung cancer progression through multiple mechanisms including increased cancer cell survival, growth, and invasiveness." (PMID 39664584, 2024). "Research on several antigens, including c-MET, DLL3, FAP, and B7-H3 (CD276), has been conducted concerning lung cancer treatment." (PMID 38694508, 2024). "Our previous publication documented that EGFR and c-MET are upstream molecules of the PI3K/Akt pathway in B[α]P and CSE-regulated lung cancer chemoresistance." (PMID 38993553, 2024). "Multiple under-expressed proteins were also predictable to a great extent, the top-performing ones being CASP8, MET, BCL2, and SETD2 in BRCA; AR and TFRC in gastric cancer; and VHL in lung cancer with AUCs ranging 0.814–0.866." (PMID 38491101, 2024).
lung cancer (continued). "In MET-amplified NSCLC, heterodimers of MET with EGFR, HER2, and HER3 activate the AKT and ERK signaling pathways, thereby enhancing lung cancer cell proliferation and survival." (PMID 39201787, 2024). "This has resulted in significant progress in the treatment of oncogene driven lung cancers such as EGFR, BRAF, MET, KRAS and HER2 mutant and ALK, ROS1, RET, NTRK1-3 translocation positive NSCLC with tyrosine kinase inhibitors (TKIs) targeting these oncogenes." (PMID 38485737, 2024). "To explore the interplay between MET, E2F1, and purine synthesis in clinical cases of lung cancer, we stratified them based on different percentiles of high and low gene expression into groups of low (25th percentile) and high (75th percentile) expression." (PMID 38957115, 2024). "The study evaluates the efficacy of c-MET-CAR-NK cells against METhigh HepG2 HCC and METlow H1299 lung cancer cells, with striking results observed, particularly in the context of HepG2 cells." (PMID 39664377, 2024). "Numerous rare fusions involving receptor tyrosine kinase (RTK) have been detected in lung cancer, including fibroblast growth factor receptor (FGFR), neuregulin 1 (NRG1), and MET Proto-Oncogene, Receptor Tyrosine Kinase (MET)." (PMID 38472960, 2024). "Yet, there is evidence suggesting that tumors harboring these gene fusions can be responsive to anti-MET monotherapy, as seen with PTPRZ1-MET in pediatric gliomas and KIF5B-MET in lung cancers." (PMID 38675409, 2024). "It was also discovered that BsAb can trigger the degradation of c-MET protein in cancer cells, encompassing both MKN45, a gastric cancer cell line, and A549, a lung cancer cell line." (PMID 39664377, 2024). "It found that single MET inhibition effectively suppresses EGFR downstream signaling and proliferation in specific lung cancer cells." (PMID 39769452, 2024). "As in lung cancer, pancreatic cancer cells are also positively regulated by the feedback loop between FOXM1 and hepatocyte growth factor (HGF)/MET signaling." (PMID 39594778, 2024). "These innovative constructs, typified by the anti-c-MET-CARs, comprise an scFv derived from an anti-c-MET antibody, CD28, and CD3ζ (responsible for signaling), with a persistent aim to inhibit c-MET in lung cancer cells." (PMID 39664377, 2024). "We looked at the distribution of breakpoints in ALK, RET, ROS1, NTRK1, as well as other kinase genes known to generate oncogenic fusions in lung cancer, such as EGFR, ERBB4, MET, FGFR3, and EPHA245." (PMID 38877018, 2024). "Li and colleagues developed and produced a novel bispecific antibody, BsAb-5, that effectively targets c-MET and CTLA-4 in lung cancer stem cell (LCSC)-like cells with a high degree of specificity and affinity." (PMID 39201787, 2024). "The oncogenic receptor tyrosine kinases are key to lung cancer malignant transformation, as evidenced by the clinical successes of EGFR, MET, and EML4-ALK inhibition by small molecule therapeutics." (PMID 38827327, 2024). "It is worth noting that MET alteration is a recurring and actionable mechanism of resistance in ALK‐positive lung cancer." (PMID 38077251, 2023). "Using a pair of MET WT and METex14 lung cancer cell lines models, we demonstrated that the HGF/MET signaling pathway plays a critical role in enhancing PD-L1 expression with higher levels of PD-L1 in METex14 cell lines compared to MET WT." (PMID 37444481, 2023). "Experiments show that MET fusion proteins respond to anti-MET monotherapy: PTPRZ1-MET in a pediatric glioma and KIF5B-MET in lung cancers." (PMID 37760640, 2023). "For example, in ERBB2-overexpressing EGFR T790M lung cancer, we controlled and degraded ERBB2 and as well degraded EGFR, MET, and YES1 kinases that are known to drive this tumor resistance to drugs." (PMID 37359373, 2023). "One of these interplays is MET–EGFR crosstalk, which was reported to be involved in therapeutic resistance to EGFR inhibitors in colon and lung cancers." (PMID 37679999, 2023).
lung cancer (continued). "Non‐small cell lung cancers with ERBB2 amplification, MET activation, KRAS G12C, RET, and ROS1 fusion resulted in the second‐highest frequency of recommendations." (PMID 36251535, 2023). "They then examined others cancer cells, including those of melanoma, lung cancer, breast cancer (BC), and colorectal cancer (CRC), and a similar DTC subpopulation was obtained after various drug treatments (cisplatin and EGFR/RAF/MET inhibitors)." (PMID 37638338, 2023). "Currently, there are several targeted therapies approved to treat lung cancer, with the targets of interest being ALK, MET, HER2, and EGFR." (PMID 36551663, 2022). "In particular, CAF-derived HGF mediates intrinsic resistance to afatinib in lung cancer by activating the MET/PI3K/AKT and MET/MAPK/ERK signaling pathways and triggering the progression of EMT and, chemoresistance development." (PMID 36359776, 2022). "Sequentially, we evaluated the targetable variations detected ability in different samples, including EGFR, ALK, BRAF V600E, KRAS, MET ex14 skipping, RET, ROS1, ERBB2, which have high evidence in lung cancer." (PMID 36167530, 2022). "Based on our integrated cohort and the TCGA LUAD cohort, we identified 28774 high-confidence alternative splicing events (ASEs), which affected 8726 genes, including targets for tyrosine kinase inhibitors used to treat lung cancer, such as EGFR, RET, and MET." (PMID 35989380, 2022). "Strategies that lead to acquired EGFR-TKI resistance, such as HGF, MET amplification, and EGFR T790M, also promote immune escape in lung cancer by upregulating the expression of PD-L1." (PMID 35840984, 2022). "Multiple additional but relatively rare oncogenic fusions have been described in lung cancers, including fusions of the FGFR, NTRK, MET, and ErbB family genes." (PMID 36369474, 2022). "We found eight genes relevant to lung cancer (PDGFRB, RET, KRAS, KEAP1, ROS1, STK11, MET and ALK), for which integrating clinical data with our TME features clearly improves the ability to predict mutations in these genes." (PMID 36131239, 2022). "Rearrangements of MET and the ErbB family RTKs (EGFR, ERBB2, ERBB3, and ERBB4) in lung cancer are less well documented and mostly as case reports." (PMID 36369474, 2022). "A previous study in 36,813 Chinese lung cancer patients, focusing on eight key lung cancer driver genes (EGFR, ALK, MET, KRAS, ERBB2, ROS1, RET, and BRAF), revealed a prevalence of 0.03% for P/LP germline mutations." (PMID 35428225, 2022). "More recently, FLT PET-CT assessment to novel targeted therapy with a c-MET inhibitor and MDM2 inhibitor in lung cancer revealed an early response at two selected time points, namely 9 days in one participant and at 4 weeks in two other participants." (PMID 36082278, 2022). "Loss of SUV420H2 facilitates upregulation of LINC01510, which promotes the transcription of the oncogene MET and EGFR inhibitor resistance in lung cancer." (PMID 36185333, 2022). "Hepatocyte growth factor (HGF) is the ligand of the proto-oncogene c-Met; it can trigger MET activation through EGFR bypass signaling and induce lung cancer resistance to EGFR-TKIs." (PMID 35840984, 2022). "Genetic testing for advanced nonsmall cell lung cancer (NSCLC) includes EGFR, ALK, ROS1, BRAF, MET, HER-2, RET, NTRK1/2/3, PI3K, and PD-L1." (PMID 35368895, 2022). "Especially in lung cancer, various targeted therapies have been developed, ranging from EGFR-TKIs and BRAF, ALK, ROS, RET, MET, TRK1, and HER2 inhibitors, to more recent developments in KRAS inhibitors." (PMID 34359729, 2021). "For instance, miR-206 was shown to be down-regulated in CDDP-resistant lung cancer cells, and overexpression of miR-206 reversed the mesenchymal features and sensitized CDDP-resistant cells to CDDP via targeting MET." (PMID 34746018, 2021). "This ethnic difference was previously reported in patients with lung cancer, and MET N375S was reported to confer resistance to c-MET inhibition." (PMID 34439385, 2021).
lung cancer (continued). "We found that METTL3 influences the expression of MET by integrating with MET to regulate PI3K/AKT pathway, which affect the response of lung cancer cells to gefitinib." (PMID 33491264, 2021). "We analyzed single-cell sequencing data from the existing research and found that the epithelial cells at the resection margin of lung cancer were more likely to highly activate the genes related to lung cancer, such as KRAS, MET, and EGFR." (PMID 34094930, 2021). "HGF decreased the barrier function of lung cancer cells, which was counteracted by SIPA1 knockdown with similarity to the small molecule MET targeted inhibitor, Crizotinib." (PMID 33917539, 2021). "First, the high alternations level on chromosome 7 hot zones are in accordance with the overexpression of nearby EGFR, MET, and BRAF genes in glioma, lung cancers, and melanoma." (PMID 34054918, 2021). "As for chromosome 7, which is widely reputed for its significant relations with the initiation and growth of lung cancer, EGFR and MET, for this chromosome, were found to play a major role with regard to lung cancer." (PMID 33503946, 2021). "Analysis of the expression levels of common immune checkpoints (PD1 and PD‐L1 in our study) and lung cancer driver genes (ALK, EGFR, ROS1, and MET in our study) between two clusters revealed significant differences in PD1, PD‐L1, and MET gene expression." (PMID 34558724, 2021). "In FGFR1-amplified lung cancer cell lines, MET-amplification is a mechanism of resistance to FGFR-targeting drugs and conversely, FGFR1-dependent resistance to MET inhibitors is observed in leukaemia, kidney and prostate cancers." (PMID 33772015, 2021). "Deregulation of PI3K/AKT signaling pathway in ALK-positive lung cancer was demonstrated by WES analysis, and significantly increased mRNA of ALK, ROS1, MET, SPP1 and PI3K signaling pathway was identified by NanoString assay." (PMID 34234236, 2021). "The existing dogma dictates that EGFR-mutant and MET-amplified lung cancers codepend on the concurrent activation of both EGFR and a MET kinases for survival, making them unresponsive to single-agent TKI treatment against either receptor." (PMID 34516823, 2021). "In other words, MET phosphorylation leads to an increase in cellular migration in ESCC and lung cancer." (PMID 34217156, 2021). "LCD inhibited lung cancer cell proliferation through ATP competitive inhibition of EGFR and MET as a single drug." (PMID 32070026, 2020). "MIR22HG was also down-regulated in lung cancer and interacts with YBX1, MET and p21 to suppress cancer development." (PMID 32500915, 2020). "Crizotinib is a low molecular weight, orally available TKI that inhibits ROS1, MET and ALK and is considered the gold standard first-line treatment with demonstrated significant activity for lung cancers harbouring ROS1 gene rearrangements." (PMID 33172113, 2020). "According to recent research, alterations in MET-activation and JAK2-inactivation are the independent factors that affect the response to immune checkpoint inhibitors like PD-L1 in lung cancer." (PMID 33014809, 2020). "SFN (stratifin) participates in the development and progression of lung cancer and stabilizes both EGFR and MET by interacting with ubiquitin-specific protease 8 (USP8)." (PMID 33023006, 2020). "We then performed western blot analyses that confirmed that both p-MET and T-MET were decreased upon LINC00857 knockdown in five lung cancer cell lines, and the decrease in MET occurred as early as 24 h after LINC00857 siRNA treatment." (PMID 33312753, 2020). "Cells were re-sensitized to PARPi with the use of a MET inhibitor, and dual MET and PARP inhibition led to synergistic anti-tumor activity in breast and lung cancer xenografts." (PMID 32722408, 2020). "Mechanistically, downregulation of LOC389641 was found to decrease EGFR, MET and STAT3 proteins expression in lung cancer cells." (PMID 33318313, 2020).
lung cancer (continued). "Consistent with this, we have previously confirmed that both MET protein and mRNA were decreased after YBX1 knockdown in lung cancer cells." (PMID 33312753, 2020). "Emerging data have suggested that MET amplification is relevant to TKI resistance in EGFR-dependent cancers, especially in lung cancer." (PMID 32435640, 2020). "MS analyses of protein phosphorylation in mouse models of human lung cancers, including those with enhanced EGFR and MET signaling, have identified phosphorylation of Tyr-1510 on IQGAP1." (PMID 33087447, 2020). "Thus, the dual inhibition of EGFR and MET might be a means to overcome lung cancer resistance." (PMID 32070026, 2020). "Activation of the HGF/MET signalling pathway has been reported to lead to the occurrence and metastasis of a variety of tumors, including CRC, breast cancer, ovarian cancer, lung cancer, and liver cancer." (PMID 32843066, 2020). "We have previously shown in lung cancer cells that GSK3α and to a lesser extent GSK3β are inhibited by the advanced clinical candidate tivantinib (ARQ197), which was designed as a MET inhibitor." (PMID 30679640, 2019). "In our study, we have also performed head-to-head comparison of EGFR, ERBB2, and MET gene amplifications between tissue WES and ctDNA in 48 lung cancer patients." (PMID 31739500, 2019). "Crizotinib, an ALK/ROS1/MET inhibitor, is highly effective against ROS1-rearranged lung cancer and is used in clinic." (PMID 31399568, 2019). "The DEGs centrally had direct interaction with EGFR, ERBB2, ERBB4, MET and TUBB, which suggested that the divergence between the primary CRC and the metastases of CRC was related to lung cancer." (PMID 30642283, 2019). "In a cohort of 262 lung cancer patients that included predominantly NSCLC and only 2 SCLC, all instances of MET activation occurred in adenocarcinomas." (PMID 30941314, 2019). "Mechanistic characterization revealed that this drug combination abrogated expression and activation of membrane receptors and downstream signaling proteins crucial in lung cancer: EGFR, MET, PAK1, PKCι, ERK1/2, AKT, YAP1 and mTOR." (PMID 31660987, 2019). "In vivo generated afatinib-resistant clones of H1975 lung cancer cells showed decreased expression of EGFR, HER2, HER3 and HER4 and increased expression of MET, c-KIT and PDGFRβ." (PMID 31557260, 2019). "The increased expression and activation of c‐MET in response to EGFR TKIs and cytotoxic anticancer agent contribute to drug resistance in lung cancer cells through compensatory enhancing of Akt signaling." (PMID 29570930, 2018). "To further examine the role of MET in EGFR-TKI-naïve cancer cells, we developed another resistant cell line from EGFR-TKI-naïve lung cancer cells, HCC827, which harbor the EGFR exon 19del." (PMID 29386539, 2018). "The activity prediction algorithm was then implemented for the regulatory networks of six important lung cancer oncogenes (FAK, PXN, MET, RON (MST1R), EPHA2, AXL)." (PMID 29731983, 2018). "In preclinical studies, foretinib significantly increases sensitivity in EGFR mutant lung cancer cells with upregulated HGF and increased MET copy number when added to erlotinib." (PMID 29050231, 2017). "We found that BsAb can induce the degradation of c-MET protein in cancer cells, including MKN45, a gastric cancer cell line, and A549, a lung cancer cell line." (PMID 28404966, 2017). "We previously provided preclinical evidence that cytotoxic drug-resistant lung cancer cells secreted HGF and accelerated its resistance by increased expression of c-MET due to gene amplification, and that c-Met inhibitors restored cytotoxic drug sensitivity." (PMID 29069748, 2017). "In fact, the crosstalk between EGFR and MET maximizes the oncogenic activity of EGFR and leads to increased migration and invasion of lung cancer cells." (PMID 28420162, 2017).